HRAS (HRas proto-oncogene, GTPase)
Diseases named in the same sentence as HRAS in open-access papers (continued):
Sharing a sentence is not in itself a finding about the gene and the disease.
thyroid cancer (continued). "In fact, the positive results of tipifarnib in a phase II clinical trial for the treatment of HRAS-mutant HNSCC and thyroid cancer (NCT02383927) has recently resulted in a Breakthrough Therapy Designation (BTD) by the FDA for the treatment of patients with recurrent or metastatic HRAS-mutant HNSCC." (PMID 34200676, 2021). "Addition of tipifarnib to existing MAPK inhibitor treatment regimens has shown promise in HRAS-driven thyroid cancer, further inhibiting ERK activation and abrogating HRAS mutant signalling." (PMID 39372214, 2024). "Many somatic genetic alterations, including those in BRAF, HRAS, KRAS, NRAS, PTEN, and HER1, have had fundamental roles in the tumorigenesis of thyroid carcinoma." (PMID 31655978, 2020). "For this purpose, we utilized the HRAS mutant cell lines C643 and HTH83, derived from thyroid carcinomas." (PMID 32927904, 2020). "In thyroid carcinoma (THCA), 5.23% were BRAF p.V600E, 0.65% were NRAS p.Q61R, and 0.25% HRAS p.Q61R." (PMID 30890735, 2019). "Many somatic genetic alterations including those in BRAF, HRAS, KRAS, NRAS, PTEN, and HER1 have been revealed to play fundamental roles in the tumorigenesis of thyroid carcinoma." (PMID 27833153, 2016). "The targeted next generation sequencing of thyroid nodules revealed BRAFV600E as the most prevalent mutation in patients with thyroid cancer (45% of examined nodules) and either no mutation or mutation in the RAS gene (NRAS Q61R, HRAS Q61K) in benign thyroid lesions." (PMID 31620364, 2019). "The HRAS G60S and KRAS H27L found in 1 ATC each, have so far not been linked to thyroid cancer." (PMID 28489587, 2017).
lung carcinoma (47 papers, 2005 to 2025). "In particular, the HRAS-mutated cell line was substituted by a lung cancer cell line with HRAS mutations, because the availability of the HRAS mutation-positive HNSCC cell line was limited." (PMID 40243851, 2025). "An oncogenic alteration in KRAS gene is the most frequent in pancreatic cancer, colorectal cancer and lung cancer, while mutated HRAS is the most common in dermatological, head and neck cancers." (PMID 33549031, 2021). "We observed that lung cancer cell lines harboring HRAS mutations showed significant higher sensitivity to MEK inhibitors than HRAS wild-type cell lines." (PMID 26544513, 2015). "Another possibility is that the erlotinib-treated tumors have mutations in other RAS genes, since a minority of RAS mutations in lung cancer have been reported to occur in N- or HRAS." (PMID 15696205, 2005). "The HRAS mutations are detected very rarely in lung cancers (< 1%)." (PMID 33549031, 2021). "HRAS mutations are observed very rarely in lung cancers (<1%)." (PMID 32850378, 2020). "However, using CRISPR-CAS 9 technology, HRAS mutation might be introduced in an appropriate lung cancer cell line in order to mimic the clinical situation." (PMID 35621690, 2022). "Through pathway enrichment analysis, we observed 14 pathways associated with lung cancer, with 12 linked to EGFR, 10 to HRAS, and 8 to MAPK8." (PMID 41155483, 2025). "It is well known that a number of head and neck carcinomas are associated with HRAS mutations, and that several cancers with RAS mutations, such as lung cancer, have a poor prognosis." (PMID 40243851, 2025). "Mutation of KRAS gene in lung cancer is more frequent than NRAS and HRAS and is often associated with poor prognosis and worse therapeutic outcome." (PMID 33549031, 2021). "The data from the current study suggest that the expression of HRAS mRNA especially is worth further evaluation as a prognostic biomarker in lung cancer." (PMID 33549031, 2021). "There are only few studies dedicated to KRAS and HRAS expression at mRNA level in lung cancer tissue." (PMID 33549031, 2021). "The HRAS and KRAS oncogene mutations are well defined, however, the clinical significance of RAS expressions in non–small-cell lung cancer (NSCLC) is still uncertain." (PMID 33549031, 2021). "KRAS is the most frequently mutated isoform in lung cancer representing 19% of the cases, followed by NRAS (1%) and HRAS (< 1%)." (PMID 32962236, 2020). "The frequency of PIK3CA, NRAS, HRAS, and PTEN mutations was higher in cfDNA than in lung cancer tissue in the cBioPortal database." (PMID 29290998, 2017). "Preclinical studies have suggested combinations of m-TOR and MEK inhibitors in KRASM lung cancers but also in N- and HRAS mutant tumours." (PMID 27441499, 2016). "Enhanced apoptosis and tumor growth suppression by combination of MEK and mTOR inhibitors was previously observed in HRAS wild-type lung cancer cell lines." (PMID 26544513, 2015). "Furthermore, reports indicated that Cpn downregulates HRAS expression in cisplatin-resistant lung cancer cells to exert antiproliferative effects." (PMID 40438591, 2025). "Indeed, the anti-tumor activity of tipifarnib shown by Gilardi and colleagues in these HNSCC HRAS mutant models was equivalent to or exceeded that reported with a combination of MAPK and PI3K inhibitors in a HRAS mutant lung cancer model." (PMID 34771475, 2021). "Finally, we included 10 well-known cancer-related genes (or their hotspot-containing exons) listed as most frequently mutated in lung cancer (BRAF,EGFR,ERBB2,HRAS,KRAS,MAP2K1,MET,NF1,NRAS, and RIT1) in the panel to serve as internal controls for highly mutated regions." (PMID 40867048, 2025).
lung carcinoma (continued). "On the contrary, those G-proteins, such as RAB5A, HRAS, and NRAS, that are modified either by two polyisoprenyl groups or a polyisoprenyl group and lipid thioester were relatively unaffected in lung cancer A549 and NCI-H1299 cells." (PMID 38540084, 2024). "A recent study has shown that the paralogues HRAS and NRAS are specific suppressors of oncogenic KRAS-driven lung cancer." (PMID 36980522, 2023). "Due to the limited data dedicated to the evaluation of the RAS genes expression in lung cancer, in current study the assessment of relative KRAS and HRAS gene expression level was performed." (PMID 33549031, 2021). "Among them, CTNNB1, ZEB1, CDC42, HSP90AA1, BST2, PCNA, and E2F1 have all been shown to promote lung cancer progression, while SAMHD1, HRAS, and NQO1 serve as tumor suppressor genes." (PMID 28498804, 2017). "To determine if the repression of HRAS and ZNF107 were sarcoma specific, we looked at their expression in senescent SNB19 glioma cells, senescent A549 and H1975 lung cancer cells and quiescent H358 lung cancer cell lines." (PMID 28855512, 2017). "Indeed, an analysis of data derived from The Cancer Genome Atlas (TCGA) revealed an inverse correlation between the expression levels of oncogenes (HRAS and AKT1) and CFLAR in breast and lung cancer samples." (PMID 34545139, 2021).
RASopathies (46 papers, 2014 to 2026). "Noonan syndrome (NS) is a RASopathy most frequently associated with mutations in HRAS, NRAS, KRAS, and RRAS2." (PMID 41517739, 2026). "The affected residues (p.Gly23, p.Thr68, p.Gln71) exhibit high evolutionary conservation across RAS family GTPases associated with RASopathies, including HRAS, NRAS, KRAS, and RRAS2." (PMID 41517739, 2026). "SLN is considered a mosaic RASopathy due to its embryological development through a postzygotic activating HRAS genetic variant." (PMID 41523454, 2025). "In this case report, we present the first case of a child with HRAS-related mosaic RASopathy presenting as SFMS and associated severe hypophosphatemia who was successfully treated with trametinib." (PMID 40611284, 2025). "This is a common finding for CS-associated HRAS variants and underscores that impaired signaling dynamics is the central pathomechanism for CS (and related RASopathies)." (PMID 35764878, 2022). "The HRAS gene is reported to contribute to germline mutations that activate RAS/MAPK signaling to lead toward “RASopathies”." (PMID 36358305, 2022). "It is known that 90% mutations of HRAS that contribute to RASopathies typically cluster to codons 12 and 13 and promote phenotypes that are detectable in infancy." (PMID 28002430, 2016). "SFMS is a mosaic RASopathy caused by postzygotic somatic activating variants in the proto-oncogenes HRAS, KRAS, and NRAS that act as small GTPases in the RAS/mitogen-activated protein kinase (MAPK) pathway, which promote variable organ manifestations and proliferative potential." (PMID 40611284, 2025). "Furthermore, genetic analysis revealed variants in genes associated with other RASopathies in four patients: HRAS (one patient), SHOC2 (two patients), and PPPCB1 (one patient)." (PMID 37568403, 2023). "In addition, Nf1 loss or HRAS-G12V RASopathy mutations have also been shown to impact mature and myelinating oligodendrocytes." (PMID 34222248, 2021). "Furthermore, it also enabled us to determine if there were differences in phenotype- or treatment efficacy compared to other mouse models of RASopathies caused by mutations in up-stream regulators of HRAS protein, such as NF1, SHP2/PTPN11, and SPRED1." (PMID 28455524, 2017). "Many of the RASopathy-associated genes are in gene families: RAF (BRAF and RAF1), RAS (HRAS, KRAS, MRAS, NRAS, RIT1, and RRAS2), MAP2K (MAP2K1 and MAP2K2), and SOS (SOS1 and SOS2)." (PMID 40496714, 2025). "Our data uncovers a new, previously unidentified mechanism capable of triggering a RASopathy phenotype in mice as a result of the combined removal of HRAS and NRAS." (PMID 38886790, 2024). "All variants are registered as pathogenic in ClinVar, and the variants that are homologous to p.Gly23Val have been reported to cause RASopathy in KRAS, HRAS, and NRAS." (PMID 38601074, 2024). "The identification of mutations in HRAS and NRAS in NS provides insight into the pathophysiology of this hamartoma, defining NS as a mosaic RASopathy." (PMID 34208656, 2021). "Postzygotic KRAS, HRAS, NRAS, and FGFR1 mutations result in a group of mosaic RASopathies characterized by related developmental anomalies in eye, skin, heart, and brain." (PMID 30891959, 2019). "Further, we compared the specific variants observed here to variants in HRAS, KRAS, or NRAS previously reported as pathogenic for RASopathies." (PMID 30500825, 2018). "Some of these genes increase predisposition to cancer, for example, in rasopathies, and BRAF, KRAS, HRAS, NF1, NRAS PTPN11, RAF129." (PMID 27080396, 2016). "Various other mosaic RASopathies, such as nevus sebaceus and non-organoid keratinocytic epidermal, have been linked to other genes, like HRAS." (PMID 41283481, 2025). "Furthermore, Lztr1R409C/+ mice exhibited splenomegaly and renal hypertrophy, consistent with those found in other RASopathy mouse models, including HRAS p.G12S and RIT1 p.A57G." (PMID 39352760, 2024).
RASopathies (continued). "The RASopathies, collectively, are a spectrum of genetic syndromes caused by mutations in genes involved in the RAS/ mitogen-activated protein kinase (MAPK) pathway, including but not limited to PTPN11, NRAS, KRAS, HRAS, BRAF, and MAP2K1." (PMID 39385823, 2024). "The proband’s daughter (III.2), who carried the same HRAS mutation, presented asymptomatic LVH and severe intellectual disability, as well as typical signs of RASopathies, including short stature, micrognathia, low-set ears with short neck, epicanthal folds and ptosis." (PMID 28002430, 2016). "In addition, we verified by exomeanalysis that the patient did not have any pathogenic variants in the genes associatedwith Noonan Syndrome and other rasopathies (PTPN11,SHOC2, KRAS, CBL,SOS1, RAF1, HRAS,NRAS, RASA1, SPRED1,BRAF, MAP2K1, MAP2K2, RIT1 andRRAS)." (PMID 27561113, 2016). "Therefore, Opn may well be a promising target to treat not only skeletal disorders arising from HRAS germline mutations in CS patients, but also other skeletal pathologies associated with increased RAS activation in RASopathies and other diseases." (PMID 40000861, 2025). "In fact, double-knockouts of HRAS and NRAS display a RASopathy-like phenotype, which contrasts to the assessment of the same double-knockout 25 years ago, i.e. at a time when many other RAS knockout studies were conducted and evaluated." (PMID 41248180, 2025). "Our data identifies the concomitant ablation of HRAS and NRAS as a new molecular alteration capable of triggering the development of RASopathy phenotypes in mice through a mechanism involving the hyperactivation of KRAS-dependent signaling." (PMID 38886790, 2024). "Expressing human RASopathy isoforms of KRAS, HRAS, RAF1, BRAF, and PTPN11 in Drosophila, we report important differences between disease isoforms including distinct signaling pathways and drug responses." (PMID 33855281, 2021). "In this report, we show that simultaneous removal of both HRAS and NRAS in mice leads to the generation of a RASopathy-like phenotype in the very small percentage of adult animals that are able to survive the perinatal period and reach adulthood in the absence of both HRAS and NRAS." (PMID 38886790, 2024). "However, little is known about the interplay between the HRAS/MAPK and the LKB1/AMPK pathway in the context of RASopathies." (PMID 35230976, 2022). "We included 63 Chinese patients with RASopathies that had previously tested negative for PTPN11 and HRAS mutations." (PMID 29402968, 2018). "At the present time, RASopathies are categorized as separate syndromes, but, as we learn more about each syndrome, clinically defining a RASopathy may be more accurately approached based on the molecular diagnosis, or gene name, such as a BRAF-based RASopathy or an HRAS-based RASopathy." (PMID 35103797, 2022). "In distinction to the known RASopathies, which are single gene disorders, the 6p25.1p24.3 microdeletion syndrome arises via transcriptional dysregulation of multiple RREB1 target genes including FGFR4, HRAS and MAP2K2 that result in sensitization of the MAPK pathway to activation." (PMID 32938917, 2020). "It is therefore reasonable that, although HRAS and NRAS are not critically needed for survival, their absence in the DKO is an essential mechanistic driver of the appearance of the defective, non-lethal RASopathy phenotypes described here." (PMID 38886790, 2024).
colorectal cancer (41 papers, 2008 to 2025). A primary or metastatic malignant neoplasm that affects the colon or rectum. "Although a previous case report identified an HRAS G13D mutation in the resistance to anti-EGFR monoclonal antibodies in colorectal cancer, this is the first report of an HRAS-activating mutation conferring acquired resistance to AZD9291 in NSCLC." (PMID 29641535, 2018). "Because KRAS mutations are involved in resistance to cetuximab in colorectal carcinoma, we next examined whether resistance to cetuximab and cisplatin, key anticancer agents for HNCs, is associated with HRAS." (PMID 40243851, 2025). "Previously, it has been assumed that the molecular profiles, such as higher frequencies of microsatellite instability–high, PTEN, and HRAS mutations, may occur in colorectal cancer patients with age <50 years than those of higher age groups." (PMID 33384992, 2020). "Mutations in the RAS gene family, encompassing KRAS, HRAS, and NRAS, represent a prevalent genetic alteration in colorectal carcinoma (CRC)." (PMID 38844562, 2024). "At the same time, DKC1‐targeted ribosomal proteins suppressed the RAS/RAF/MEK/ERK pathway via interaction with HRAS, and combination therapy with PF and trametinib exhibited synergistic anticancer efficacy in colorectal cancer cells." (PMID 34026451, 2021). "It is also evident that KRAS and HRAS oncogenes differentially regulate autophagic cell properties in the examined colorectal cancer cells." (PMID 26802026, 2016). "A study of the proteome of the intermediate-stage colorectal cancer cell line Caco2 revealed that the mutant KRAS (V12) contributed to an increased H-Ras protein level, indicating that HRAS might be a pivotal factor involved in the effects of KRAS mutation." (PMID 38481800, 2024). "In addition to KRAS mutation, genetic alterations in NRAS, HRAS, BRAF, and RAF1 were found in colorectal cancer samples analyzed in this study." (PMID 23700467, 2013). "Similarly, the KRAS G12C inhibitors sotorasib and JDQ443 had also displayed inhibitory effects on HRAS G12C and NRAS C12C, with the combination therapy of sotorasib and EGFR antibody panitumumab being successfully used to treat a patient with colorectal cancer with NRAS p.G12C mutation." (PMID 40304209, 2025). "Furthermore, other than HRAS G13D, we did not identify any new colorectal cancer driver mutations in the tumours during or post-NACRT." (PMID 32640573, 2020). "These new experiments further support a mechanism in which cetuximab inhibits wild-type (HRAS and NRAS) signals in KRAS G13D colorectal cancers." (PMID 33153459, 2020). "Other mutual exclusivities have been observed between HRAS and RHOA, in head and neck squamous cell carcinoma (HNSC) and between DIRAS2 and KRAS in colorectal cancer." (PMID 26860319, 2016). "We identified this complex in every PDX sample evaluated, including PDXs from lung, pancreatic and colorectal cancers with mutant KRAS, mutant HRAS or mutant NRAS and from the HBEC line as well as from the WI-38 nonimmortalized nontransformed human lung fibroblast line." (PMID 39528835, 2024). "Its transcriptional activity was regulated by MAPK effector Egr-1, which could be activated by RTK ligands or mutant HRAS, on the other hand, both LY294002 and wortmannin, inhibitors of PI3K, could efficiently down-regulate KLF5 promoter transcriptional activity in DLD-1 colorectal cancer cells." (PMID 26544730, 2015).